RN7SKP2 (RN7SK pseudogene 2)
Gene: Miscellaneous RNA gene on chromosome 13 (40,407,122 to 40,407,440, reverse strand). Ensembl gene ENSG00000252812.
Homologues: Orthologues: chimpanzee 7SK (99% identical), mouse Gm54538 (39% identical). Paralogues in human: 7SK (52% identical), RN7SKP160 (52% identical), RN7SKP30 (52% identical), RN7SKP48 (51% identical), RN7SKP227 (51% identical), RN7SKP178 (51% identical), RN7SKP62 (51% identical), RN7SKP118 (50% identical), RN7SKP180 (50% identical), RN7SKP170 (50% identical), RN7SKP127 (50% identical), RN7SKP162 (50% identical), and 284 more.